ERBB2 (erb-b2 receptor tyrosine kinase 2)
Diseases named in the same sentence as ERBB2 in open-access papers (continued):
Sharing a sentence is not in itself a finding about the gene and the disease.
breast cancer (continued). "An adjuvant therapy trial evaluating celecoxib in ERBB2-negative breast cancer patients found no significant improvement in DFS following two years of treatment as an add-on to standard therapy." (PMID 40563367, 2025). "Notably, the current study reveals a new role of Nuclear Protein 1 (NUPR1/P8/COM1) in regulating the expression of HDAC5, ERBB2 (and the survival reliance switch from estrogen to EGF) and BIRC5 (a well-known oncogene) in breast cancer cells." (PMID 39991577, 2025). "Overall, the incidence rate of HR-positive and ERBB2-negative breast cancer for all races and all ages increased by 1.9% per year from 2010 to 2019." (PMID 39853979, 2025). "Breast cancer is divided into 3 main subtypes based on molecular markers for estrogen (ER) or progesterone (PR) receptors and human epidermal growth factor 2 (ERBB2; formerly HER2), and triple negative (tumors lacking all three standard molecular markers)." (PMID 40576246, 2025). "Notably, AKT1, ERBB2 (HER2), CDK4, and CCNE1 are significantly amplified in tumor samples while PIK3CA displays the lower expression level in breast cancer." (PMID 40725120, 2025). "Despite these advancements, most patients with hormone receptor–positive/ERBB2–negative metastatic breast cancer experience disease progression during first-line ET plus CDK4/6i treatment due to the development of acquired tumor resistance." (PMID 39982725, 2025). "The findings highlight the variability in genomic assay use to facilitate adjuvant therapy recommendations for HR-positive, ERBB2-negative breast cancer." (PMID 41632146, 2025). "Breast cancer can be classified into three subclasses based on the expression of the estrogen receptor (ER), progesterone receptor (PR), and ERBB2 gene amplification (HER2)." (PMID 40668275, 2025). "Several examples have reached the clinical setting, such as those acting against the membrane protein TROP2, a cellular receptor involved in calcium signaling and linked to oncogenesis, in triple-negative breast cancer or ErbB2 in HER2-positive breast cancer." (PMID 40647506, 2025). "All adenosquamous carcinomas in the TSG101-induced mammary tumor model lacked expression of the estrogen and progesterone receptors as well as amplification of ERBB2." (PMID 40624726, 2025). "These include alterations such as in ERBB2 (HER2), which is frequently amplified in aggressive breast cancer subtypes, or PTEN (phosphatase and tensin homolog), a tumor suppressor gene that, when deleted or mutated, can lead to the activation of the PI3K/AKT signaling pathway." (PMID 40075655, 2025). "The cohort included women with stage I to III, HR-positive, ERBB2-negative breast cancer who had undergone a lumpectomy or mastectomy and were eligible for endocrine therapy." (PMID 41632146, 2025). "Overall, 178 of 264 individuals (67.4%) had triple-negative breast cancer, 75 (28.4%) had ER- and/or PR-positive ERBB2-negative breast cancer, and 11 (4.2%) had ERBB2-positive breast cancer." (PMID 39964682, 2025). "For example, using ErbB2/Neu transgenic mice, it has been shown that inhibition of PI3Kγ effectively protects against AIC, while inducing anti‐tumour immune responses, leading to reduced mammary cancer growth." (PMID 40069106, 2025). "To understand Srsf3-induced changes in RNA splicing, we performed alternative splicing analysis using rMATS and identified 1118 Srsf3-responsive splicing events in 899 genes in Erbb2 breast cancers with or without Srsf3 KO." (PMID 40568073, 2025).
breast cancer (continued). "Among these breast cancer subtypes [luminal A, luminal B, ERBB2/HER2-positive, and triple-negative (TNBC) breast cancer], luminal A (ER+ and/or PR+, ERBB2-, low Ki-67) is the most common type, which accounts for approximately 40% of all breast cancer cases." (PMID 39991577, 2025). "The study population was ascertained from a pathology database rather than from a genetics or clinical database to minimize bias and included patients regardless of age at breast cancer diagnosis, hormone receptor positivity, or ERBB2 amplification status." (PMID 39964682, 2025). "The findings highlight the variability in genomic assay use to inform adjuvant systemic therapy recommendations in HR-positive, ERBB2-negative breast cancer." (PMID 41632146, 2025). "Consistently with Erbb2 cancer tissues, knockdown of Srsf3 expression in mouse Erbb2+ NF639 cells and two human breast cancer cell lines ER+ MCF7 and HER2+ SKBR3 cells was also found to promote exon 11 inclusion of Eif4a2 and subsequently to inhibit the production of eIF4A2 protein." (PMID 40568073, 2025). "Similarly, in HER2+ breast cancer, IGF-1R cooperates with HER2/ERBB2 signaling to sustain downstream PI3K/AKT and MAPK activation, thereby undermining the efficacy of HER2-targeted agents such as trastuzumab." (PMID 41157306, 2025). "In breast cancer cells, PTPN9 directly dephosphorylates EGFR and ErbB2, attenuating downstream STAT3/STAT5 signaling, suggesting that PTPN9 status could influence responses to EGFR-directed TKIs." (PMID 41275311, 2025). "This cohort study was conducted at a comprehensive cancer center among patients aged 50 to 69 years with T1N0, hormone receptor–positive, ERBB2-negative breast cancer, with an ODX RS of 18 or below." (PMID 40960828, 2025). "Clinically, based on the expression of hormone receptors: estrogen receptor (ER), progesterone receptor (PR) and HER2 (human epidermal growth factor receptor 2, ERBB2), breast cancer is classified into three major subtypes: Luminal, HER2-enriched and triple-negative breast cancer (TNBC)." (PMID 41372129, 2025). "In comparison, in human breast cancer (MCF-7) cells expressing both α2β1 integrins and a constitutively active receptor tyrosine kinase (ErbB2), cell surface pH is 7.05, and only an increase to 7.2 by means of NHE1 inhibition leads to optimum migration on collagen I." (PMID 38214759, 2024). "Moreover, we investigated the presence of CD45+ CTCs in CRC, breast cancer (BC) and NSCLC patients by detecting the epithelial-mesenchymal markers EpCAM, Vimentin, or abnormal expression of ERBB2, or CK." (PMID 38575583, 2024). "We aimed to investigate the prognostic significance of manual scoring and digital image analysis (DIA) algorithm assessment of HER2 copy numbers and HER2/CEP17 ratios, along with ERBB2 mRNA levels among early-stage HER2-positive breast cancer patients treated with trastuzumab." (PMID 38321542, 2024). "Young patients with breast cancer with estrogen receptor (ER)–positive, ERBB2-negative tumors have a poor prognosis." (PMID 39509133, 2024). "This retrospective cross-sectional study included women aged 70 years or older who were diagnosed with HR+/ERBB2-negative (ERBB2−) breast cancer from January 1, 2013, to December 31, 2017." (PMID 39446322, 2024). "The presented model predicts high nodal burden in patients with luminal ERBB2-negative T1-T3 breast cancer and 1 or 2 SLN macrometastases with good performance measures." (PMID 39320882, 2024). "Dual-targeted CAR-T cells have been shown to be effective against breast cancer too, for example, with CAR-T cells equipped with a split dual-antigen targeting system that required simultaneous activation upon engagement with ErbB2 and MUC1 TAAs." (PMID 39596267, 2024).
breast cancer (continued). "This large, multicenter, retrospective cohort study included 2772 patients with ER-positive, ERBB2-negative breast cancer and had a long median follow-up duration of 10.8 years." (PMID 39509133, 2024). "For example, Kadcyla (Trastuzumab emtansine/T-DM1)is effective in the treatment of ERBB2-positive breast cancer, but it has not delivered remarkable clinical benefit in ERBB2-positive gastric cancer." (PMID 39060958, 2024). "HuR binds to the 3′UTR of ERBB2 and positively impacts its expression by increasing the stability of the transcripts, while upregulation of miR26a/b represses ERBB2 expression, thereby conferring higher sensitivity to tamoxifen in MCF7 breast cancer cell lines." (PMID 38328550, 2024). "All patients had unilateral breast cancer; most tumors were invasive ductal carcinoma (39 [80%]), and most were hormone receptor positive and ERBB2 negative (38 [78%])." (PMID 38578640, 2024). "Triple-negative breast cancer (TNBC), lacking the expression of ER, PR, and ErbB2/HER2, presents the poorest prognosis among breast cancer subtypes, with chemotherapy as standard treatment." (PMID 38892243, 2024). "Breast cancer can be categorized into three major subtypes: hormone receptor-positive/ERBB2-negative, ERBB2-positive, and triple-negative; triple-negative breast cancer (TNBC) is the most aggressive subtype." (PMID 39194515, 2024). "Adding fulvestrant to anastrozole (A+F) improved survival in postmenopausal women with advanced estrogen receptor (ER)–positive/ERBB2 (formerly HER2)–negative breast cancer." (PMID 38236590, 2024). "RhoC overexpression did not affect ERBB2 protein accumulation in transfected breast cancer cells in vitro." (PMID 38807216, 2024). "Prediction models were developed by multivariable logistic regression in the complete luminal ERBB2-negative cohort and a lobular breast cancer subgroup." (PMID 39320882, 2024). "Breast cancer is categorized into three primary subtypes based on the presence of hormone receptors (ER and PR) and HER2 (ERBB2) status: luminal ER-positive and PR-positive, which can be further divided into luminal A and B; HER2-positive; and triple-negative breast cancer (TNBC)." (PMID 39247184, 2024). "Several clinical trials have consistently demonstrated that patients with breast cancer benefit from targeted therapies, such as HER2-targeted agents, only if they exhibit HER2 protein overexpression or amplification of the ERBB2 gene confirmed via in situ hybridization (ISH) techniques." (PMID 39335113, 2024). "Is age an independent factor associated with late distant recurrence among young patients with breast cancer with estrogen receptor (ER)–positive, ERBB2-negative tumors?" (PMID 39509133, 2024). "In specific, there are three major subtypes of breast cancer: hormone-receptor-positive/ERBB2-negative, ERBB2-positive, and, lastly, triple-negative breast cancer." (PMID 38672636, 2024). "In this randomized clinical trial, neither fulvestrant nor A+F significantly improved the 6-month ESDR over anastrozole in ER-rich/ERBB2-negative breast cancer." (PMID 38236590, 2024). "Breast cancer is classified into different subtypes based on the presence or absence of specific protein markers, namely estrogen receptor α (ERα), progesterone receptor (PR), and ERBB2 (also known as Human Epidermal Growth Factor Receptor 2, HER2)." (PMID 39519045, 2024). "Estrogen receptor-positive, ErbB2 (formerly HER2/neu)-negative (ER+ErbB2-) breast cancer is typically endocrine therapy sensitive and poorly responsive to systemic chemotherapy." (PMID 39006626, 2024). "RNA-seq analysis of SLFN12-over-expressing xenografts reveals expression of less aggressive breast cancer markers HER2 receptors ERBB2 and EGFR that usually are absent in TNBC." (PMID 38791884, 2024). "Among the various subtypes of early‐stage invasive breast cancer (EBC), estrogen receptor‐positive, ERBB2‐negative (ER+/ERBB2‐) breast cancer accounts for approximately 60% of cases." (PMID 39031010, 2024).
breast cancer (continued). "Finally, as an additional validation of ERBB2 as a potential mechanism of resistance to HER3-DXd, we assessed HER2DX ERBB2 in the baseline tumors of a cohort of 30 breast cancer patient-derived xenografts (PDXs) treated with HER3-DXd16." (PMID 38992028, 2024). "Our findings also showed that breast cancer patients with TOP2A, ERBB2, and MYC amplification (amp) achieved higher pCR rates than wtTOP2A, ERBB2, and MYC (56.3% (n=1) vs 13.8% (n=1), 28.4% (n=1) vs 6.1% (n=1), and 13.7% (n=1) vs 11.2% (n=1), respectively) when treated with TA regimens." (PMID 38576013, 2024). "Postmenopausal women with clinical stage II to III, ER-rich (Allred score 6-8 or >66%)/ERBB2-negative breast cancer were included." (PMID 38236590, 2024). "Human epidermal growth factor receptor 2 metabolomics studies, also known as ERBB2-positive breast cancer, have shown that patients who responded well to trastuzumab-paclitaxel neoadjuvant therapy had higher levels of serum SPD than those who responded poorly, and lower levels of tryptophan." (PMID 38256070, 2024). "Although the ERBB2 status of mammary tumours in canines is not yet considered in veterinary medicine, it is essential to note that trastuzumab has been shown to significantly inhibit the proliferation of canine mammary carcinoma cell lines in vitro." (PMID 38787171, 2024). "In breast cancer, lapatinib may be used to inhibit EGFR and erb-b2 receptor tyrosine kinase 2 (HER2) kinases, two receptors of also relevant function in TC." (PMID 38779099, 2024). "MCL1 copy number variations have been seen in triple negative, hormone receptor positive and ERBB2-positive breast cancer and have been correlated with both prognosis and resistance to various antitumor therapies." (PMID 38523186, 2024). "Trastuzumab (Trast), also known as Herceptin, is a humanized monoclonal antibody targeting the extracellular domain of erythroblastic leukemia viral oncogene homolog-2 also known as HER2 (ErbB-2/HER-2), which is overexpressed in 25–30% of breast cancers and their metastases." (PMID 39339166, 2024). "This diagnostic/prognostic study evaluates prediction models for high nodal burden in luminal ERBB2-negative breast cancer." (PMID 39320882, 2024). "Artificial overexpression of the presumed breast cancer-specific oncogenes, such as HER2/ERBB2, may advance breast cancer research in transgenic mice." (PMID 39329990, 2024). "Retaspimycin hydrochloride was evaluated in clinical trials for non-small cell lung cancer (NSCLC) and for ERBB2-positive breast cancer, but it failed to meet the criteria for study expansion." (PMID 39457075, 2024). "In this study, an association between West African genetic ancestry and breast cancer DFS among participants with HR-positive/ERBB2-negative breast cancer was observed, even after controlling for potential clinicopathologic and SDOH confounders." (PMID 39652347, 2024). "Most women in the cohort presented with estrogen receptor (ER)–positive, ERBB2 (formerly HER2 or HER2/neu)–negative breast cancer (487 of 729 [66.8%]), while 15.4% of the cohort (112 of 729) had TNBC." (PMID 39226054, 2024). "Of 1010 patients with luminal ERBB2-negative breast cancer assigned to CALND in the SENOMAC trial (luminal cohort; median [range] age, 61 years; 1006 [99.6%] female and 4 [0.4%] male), 138 (13.7%) had a high nodal burden." (PMID 39320882, 2024). "A total of 18 cancer genes including ERBB2/HER2, ATR, ESR1 and MAP3K1 were identified to be LateN-to-EarlyT replicated in BRCA and affected by an APOBEC3-mediated omikli event in at least one tumour in the breast cancer cohort." (PMID 39019871, 2024). "In both cases, the patients had aggressive hormonal receptor-positive (ER and PR) ErbB2-negative breast cancers with nodal involvement and distant metastases." (PMID 39497719, 2024).
breast cancer (continued). "In clinical practice, the molecular subtyping of breast cancer (BC) relies on immunohistochemistry (IHC) to measure the protein expression of estrogen receptor ER/ESR1, progesterone receptor PR/PGR, human epidermal growth factor receptor 2 HER2/ERBB2, and marker of proliferation Ki67/MKI67." (PMID 38337757, 2024). "This large-scale retrospective cohort analysis found minimal prognostic differences between ERBB2-low and ERBB2-negative breast cancer." (PMID 36821125, 2023). "We have used EO771 cells, which is a murine luminal B mammary cancer cell line (estrogen receptor α negative, estrogen receptor β positive, progesterone receptor positive and ErbB2 positive), originally isolated from a spontaneous tumor in a C57BL/6 mouse." (PMID 36978895, 2023). "Yu et al22 evaluated the noninferiority of an anthracycline-free or short-term regimen to the standard anthracycline-based regimen for patients with operable ERBB2-negative breast cancer." (PMID 36826820, 2023). "Neoadjuvant immunotherapy is also being tested in ERBB2-negative early breast cancer in combination with olaparib (I-SPY), in ERBB-2-positive breast cancer (neoPATH, IMPASSION 051) and hormone-receptor-positive breast cancer (GIADA trial)." (PMID 37511609, 2023). "We did not identify copy number level changes in ERBB2, in agreement with published cohorts in breast cancer brain metastasis which show no amplification of ERBB2 but increased ERBB2 expression in brain metastases compared to their matched primary tumours." (PMID 37973922, 2023). "Especially in the treatment of patients with hormone receptor (HR)-positive and ERBB2 (formerly HER2)-negative advanced breast cancer, CDK4 and CDK6 inhibitors (abemaciclib, ribociclib, and palbociclib) have an important role." (PMID 36945921, 2023). "In the said study, four breast cancer cell lines with variable levels of the expression of these two markers were used to research the effects of metformin used in vitro, including MCF-7 and MCF-7/713 (MCF-7 transfected with erbB2, BT-474, and SKBR-3)." (PMID 36766896, 2023). "The SK-BR-3 breast cancer cell line was derived in the same year as AU565, from the same 43-year-old white female through the pleural effusion metastasis that has similar characteristics of overexpression of the ErbB-2 gene product." (PMID 38137912, 2023). "In breast cancer, PD-1/PD-L1 may affect various signaling pathways, such as PTEN/PIK3CA, ERBB2 and STAT3, affecting various biological processes of tumor cells and the interaction between tumor cells and immune cells." (PMID 37154982, 2023). "Previous studies have also suggested that the PTPN1 protein level is dramatically increased in breast cancer tissues and that PTPN1 promotes the proliferation and suppresses the apoptosis of both ErbB2-positive and triple-negative breast cancer (TNBC) cell lines." (PMID 37936713, 2023). "HER2 (ERBB2), a known proto-oncogene, is located at the long arm of human chromosome 17 whose overexpression, and hence their receptors, is present in about 20–30% of breast cancers as a result of amplification of the chromosomal region 17q12-211." (PMID 37258548, 2023). "Patients with hormone receptor–positive, ERBB2-negative, lymph node–positive operable breast cancer were included and randomized into 2 treatment groups." (PMID 36826820, 2023). "Our study revealed the feasibility of a cyclophosphamide-free regimen as adjuvant chemotherapy in operable ERBB2-negative breast cancer." (PMID 36826820, 2023). "Human epidermal growth factor receptor 2 (HER2), as a prognostic and predictive factor, is overexpressed as a result of the amplification of the ERBB2 gene, part of the epidermal growth receptor factor (EGFR) family, in about 15% of breast cancers." (PMID 37835372, 2023).